CTLA4 (cytotoxic T-lymphocyte associated protein 4)
Diseases named in the same sentence as CTLA4 in open-access papers (continued):
Sharing a sentence is not in itself a finding about the gene and the disease.
melanoma (continued). "While combined immune checkpoint blockade of programmed death-1 (PD-1) and cytotoxic T-lymphocyte-associated protein 4 (CTLA-4) demonstrates intracranial efficacy in a proportion of patients with melanoma, the responses are rarely durable, particularly in patients with symptomatic BrM." (PMID 39551601, 2024). "Starting with the approval of anti-cytotoxic T lymphocyte-associated protein 4 (anti-CTLA-4) for advanced-stage melanoma in 2011, ICIs have obtained US Food and Drug Administration approval for the treatment of a wide array of cancer types, demonstrating unprecedented extension of patient survival." (PMID 38391750, 2024). "Moreover, increased butyrate and propionate concentrations have been linked to CTLA4 blockade resistance in murine models and patients with melanoma." (PMID 38617537, 2024). "In this study, we found higher expression levels of the immune checkpoint molecules (CTLA-4, PD-1, PD-L1, etc.)in the low-risk group, indicating that these melanoma patients may have a more favorable response to ICIs." (PMID 37205993, 2023). "Further, while combination ICT (anti-PD-1 and anti-CTLA-4) has been shown to be more effective than single agent ICT in melanoma, combination therapy is also associated with a higher incidence of immune-related adverse events, including colitis, in cancer patients." (PMID 36867675, 2023). "Moreover, a previous study analyzed several public cohorts and showed that patients with HRR mutations had better outcomes after anti‐CTLA‐4 treatment in advanced melanoma." (PMID 37986697, 2023). "Furthermore, the antitumor effect of anti-cytotoxic T-lymphocyte-associated protein 4 (anti-CTLA-4) antibodies was associated with the presence of distinct Bacteroides species that were able to stimulate the T cell response against melanoma." (PMID 38046824, 2023). "Programmed death-1/ligand 1 (PD-1/PDL-1) inhibitors and cytotoxic T-lymphocyte-associated protein-4 (CTLA-4) inhibitors have shown significant potential in improving overall survival (OS) in patients with malignant melanoma, non-small cell lung carcinoma, renal cell carcinoma, and other tumors." (PMID 37476113, 2023). "A 2017 observational study that analyzed real-world tumor responses in patients with NSCLC or advanced melanoma who received denosumab in combination with CTLA-4 or PD-1 inhibitors showed a significant association between longer exposure to concomitant therapy and ORR." (PMID 37929901, 2023). "Nivolumab, an anti-PD-1 mAb, and ipilimumab, an anti–CTL-associated antigen 4 (CTLA-4) mAb, are immune checkpoint inhibitors that have shown antitumor activity in several malignancies, including melanoma, renal cell cancer, lung cancer, and hepatocellular cancer." (PMID 37621406, 2023). "In an initial clinical trial where an anti-CTLA-4 blocking antibody was administered to patients with metastatic melanoma in combination with peptide vaccines containing melanoma-associated antigens, 43% of patients (6 out of 14) experienced grade III/IV autoimmunity affecting multiple organs." (PMID 37614504, 2023). "Specifically in melanoma, high dosage of arm- or chromosome-level SCNAs were associated with poorer response to anti-CTLA-4 in a retrospective analysis, one such example being gains in chromosome 7 that are accompanied by poor lymphocyte infiltrate and aberrant neutrophil activation." (PMID 36674809, 2023). "Single agent anti‐PD1 therapy, anti‐CTLA4 therapy or combination immunotherapy is associated with long term survival in a real‐world population of both treatment naïve and pre‐treated patients with advanced melanoma, NSCLC and RCC." (PMID 36404632, 2023). "This may not be a universal feature, because in some cohorts high levels of fecal Faecalibacterium is associated with worse prognosis in patients with malignant melanoma and fecal butyrate limits the anticancer effect of CTLA-4 blockade." (PMID 37555952, 2023).
melanoma (continued). "Till now, three immune checkpoint inhibitors have been approved by the FDA for the treatment of melanoma, including ipilimumab against cytotoxic T lymphocyte-associated antigen 4 (CTLA-4), as well as pembrolizumab and nivolumab against programmed cell death protein 1 (PD-1)." (PMID 36908706, 2023). "All β1, β2, and β3 adrenergic receptors are expressed in peripheral blood monocytes, activated T cells, monocytes, and monocyte-induced dendritic cells, and combinatorial sympathetic and cytotoxic T-lymphocyte-associated protein 4 (CTLA-4) blockade can inhibit the growth of murine melanoma." (PMID 37347365, 2023). "Interestingly, the melanoma resistance of mice treated with LPPC/MP/CD28 complexes would be reversed to susceptible after administration with LPPC/MP/CTLA4 complexes." (PMID 36691089, 2023). "ICI targeting the programmed death receptor (ligand) 1 (PD-1/PD-L1) and cytotoxic T-lymphocyte-associated protein 4 (CTLA-4) axis are widely applied in solid malignancies such as melanoma, lung cancer, renal cell carcinoma, head and neck squamous cell carcinoma, among others." (PMID 36181606, 2023). "Based on our results, male sex, lung cancer, melanoma, and treatment with anti-PD-1, anti-PD-L1, or anti-PD-1 in combination with CTLA-4 may increase the risk of ICI-associated myocarditis." (PMID 37876928, 2023). "Our study provides new insights into the underlying mechanisms of reduced CTLA4 expression observed in melanoma patients, demonstrating that post-transcriptional silencing of CTLA4 by miR-155 in Treg cells may play a critical role." (PMID 37197667, 2023). "In comparison to anti-CTLA-4, Pembrolizumab, Nivolumab, and anti-PD-1 antibodies which are associated with increased viability of patient with metastatic melanoma, the Ipilimumab is on first stage of wild melanoma treatment with metastatic BRAF." (PMID 37605149, 2023). "Ipilimumab, a medication that targets the CTLA-4 protein, was ineffective against melanomas that had deletions (copy number loss) of crucial IFNγ pathway genes including IRF1, IFT1/2, and amplifications (copy number increase) of IFNγ-related pathway inhibitors like SOCS1 and PIAS4." (PMID 37038154, 2023). "We found that PD-L1 expression lower than 1% in tumor and immune cells, a line of immunotherapeutic treatment other than the first line, an acral lentiginous histological melanoma subtype, and an anti-CTLA-4 treatment as monotherapy were associated with poor responses." (PMID 36980349, 2023). "Besides urothelial cancer, previous studies also indicate there is a relationship between CTLA-4 -318 C/T polymorphism in cervical cancer, leukemia, melanoma, thymoma, lymphoma, skin cancer, and breast cancer." (PMID 38046481, 2023). "Additionally, another study reported that CTLA4 methylation in tumors, which leads to reduced CTLA4 mRNA, is associated with resistance to anti-PD-1 and anti-CTLA-4 immunotherapy in melanoma patients." (PMID 37197667, 2023). "Interestingly the same parameter showed an association with a lower chance of response to anti-CTLA-4 agents in melanoma." (PMID 36674809, 2023). "Heterogeneous ribonuclear protein A18 (hnRNP A18) is an RNA binding protein (RBP) involved in the hypoxic cellular stress response and regulation of cytotoxic T-lymphocyte-associated protein 4 (CTLA-4) expression in melanoma, breast cancer, prostate cancer, and colon cancer solid tumors." (PMID 36539586, 2023). "However, in melanoma with glycolytic deficiency, blockade of CTLA-4 promotes infiltration and metabolic adaptation of immune cells, increases peripheral Tregs and induces its production of IFN-γ, ultimately improving the immune effect." (PMID 36620597, 2022). "The AUC of the risk signature predicted the OS of melanoma treated with CTLA4 is 0.74." (PMID 35924232, 2022). "Moreover, in melanoma patients treated with the CTLA4 inhibitor, LIAS expression was negatively linked with infiltration of CTL." (PMID 35982953, 2022).
melanoma (continued). "Studies in patients with melanoma have demonstrated that baseline microbiota compositions with a higher representation of bacteria belonging to the Bacteroidetes phylum are associated with resistance to the development of CTLA-4-induced colitis." (PMID 35565190, 2022). "Another study has emphasized that circulating B lymphocytes produce tumour necrosis factor α (TNF-α) and/or IL-6, these being associated with tumour unresponsiveness and poor survival of melanoma patients who underwent anti-cytotoxic T-lymphocyte associated protein 4 (CTLA4) antibody therapy." (PMID 35334544, 2022). "Then, we compared the expression profiling of AA1 and AA2 with the melanoma dataset containing 47 patients who received a programmed cell death protein-1 (PD-1) immune checkpoint inhibitor or cytotoxic T-lymphocyte-associated protein-4 (CTLA-4) immune checkpoint inhibitor." (PMID 36341436, 2022). "Our group repeatedly demonstrated aberrant methylation levels of immune checkpoint genes [i.e. PD-1, PD-L1, PD-1 ligand 2 (PD-L2), 4-1BB, LAG3, and cytotoxic T-lymphocyte associated protein 4 (CTLA4)] with a predictive and prognostic value in different malignancies including melanoma." (PMID 35410311, 2022). "In mouse melanoma models, activation of the β-catenin pathway in melanoma cells is associated with low/absent tumor-infiltrating lymphocytes (TILs) in tumors and resistance to anti-PD-L1/anti-CTLA-4 antibody therapy." (PMID 34986841, 2022). "Higher levels of CXCL9, CXCL10, and CXCL11 were also detected in melanoma patients’ tumors following treatment with ipilimumab, an antagonistic antibody against cytotoxic T-lymphocyte-associated protein 4 (CTLA4), another inhibitory receptor expressed by T cells." (PMID 33603130, 2022). "In addition, we show that Activin-A/INHBA expression correlates with anti-PD1 therapy resistance in melanoma patients and impairs the response to dual anti-cytotoxic T-Lymphocyte associated protein 4/anti-PD1 treatment in preclinical models." (PMID 35580932, 2022). "Immunotherapy has transformed the management of patients with advanced melanoma, with five-year overall survival rates reaching 52% for combination immunotherapies blocking the cytotoxic T-lymphocyte-associated antigen-4 (CTLA4) and programmed cell death-1 (PD1) immune axes." (PMID 36230753, 2022). "Subclass mapping was used to compare the expression profiles of the two groups with the dataset of an open melanoma treatment cohort of 47 melanoma patients receiving programmed cell death protein-1 (PD-1) or cytotoxic T lymphocyte-associated protein-4 (CTLA-4) immunosuppression." (PMID 35589807, 2022). "With the rapid development of Immune Checkpoint Inhibitors (ICIs), antibodies against programmed cell death protein 1(PD-1), Programmed cell death-ligand 1(PD-L1)and cytotoxic T-lymphocyte-associated protein 4(CTLA-4) have been approved one after another for the treatment of melanoma." (PMID 36419893, 2022). "The one-year absolute risk of cardiac events was 6.6% (95% CI: 1.8–11.3) in melanoma patients treated with PD-1 inhibitors, 7.5% (3.7–11.3) in melanoma patients treated with CTLA-4 inhibitors, and 9.7% in lung (95% CI: 6.8–12.5) cancer patients treated with PD-1 inhibitors." (PMID 35267453, 2022). "Although the extent of contribution of ADCC/ADCP to the clinical outcomes of ipilimumab (an IgG1-form mAb targeting CTLA-4) has not been fully understood, it has been documented that human FcγR polymorphisms impact responses to ipilimumab in patients with advanced melanoma." (PMID 35273608, 2022). "Moreover, increased expression of interferon-related genes (e.g., CXCL4, CXCL5, CXCL10, ID O 1, IRF1, STAT1 and others) was associated with benefit from anti-PD-1 and anti-CTLA-4 immunotherapy in melanoma patients." (PMID 35495634, 2022).
melanoma (continued). "Taken together, these findings suggest that further enhancement of FcγR effector function of anti-CTLA-4 may result in increased anti-tumour activity, and FcγRIIIa-158V/F polymorphism is linked to ipilimumab response in melanoma patients." (PMID 35814459, 2022). "In contrast with preclinical data suggesting that activation of the β-catenin pathway in melanoma cells associates with resistance to anti-PD-L1/anti-CTLA-4 antibody therapy, we found that more than 50% of patients with APC/CTNNB1 genetic aberrations responded to immunotherapies." (PMID 34986841, 2022). "Indeed, we confirmed that an increased i.t./stromal CXCL12 level was associated with therapeutic benefits in patients with melanoma undergoing anti–CTLA-4 immunotherapy." (PMID 35552271, 2022). "Treatment with CTLA-4 inhibitors alone or PD-1 inhibitors in combination with intralesional interleukin-2 in melanoma patients may lead to an AEC increase, associated with improved progression-free and overall survival." (PMID 35936009, 2022). "In addition, the number of total neoantigens and neoantigens from missense mutations can predict patient response in melanoma CTLA4 and NSCLC PD1 cohorts." (PMID 36139377, 2022). "In 2011, the US Food and Drug Administration (FDA) approved the first immune checkpoint inhibitor (ICI) targeting cytotoxic T‐lymphocyte‐associated protein 4 (CTLA‐4 or CD152), after it became the first drug ever shown to improve survival for patients with advanced melanoma." (PMID 35394069, 2022). "A previous report has revealed that the melanoma cell-intrinsic Wnt/β-catenin signaling activation is associated with the nonexistence of a T-cell gene expression signature, rendering the resistance to anti-PD-L1/anti-CTLA-4 monoclonal antibody treatment." (PMID 36429010, 2022). "Programmed cell death protein 1 (PD-1), programmed cell death 1 ligand 1 (PD-L1), and cytotoxic T-lymphocyte-associated protein 4 (CTLA-4) inhibitors have been approved for the treatment of a variety of tumors, including lung cancer, melanoma, renal cancer, and classic Hodgkin lymphoma (cHL)." (PMID 35559250, 2022). "Nowadays, multiple immune checkpoint inhibitors that block programmed cell death protein 1 (PD1) and cytotoxic T lymphocyte-associated antigen 4 (CTLA4) are used for the treatment of multiple cancers like melanoma, kidney and non-small-cell lung carcinomas, etc.." (PMID 36700224, 2022). "ICIs were initially studied and applied for the clinical application in melanoma, and Ipilimumab, targeting cytotoxic T-lymphocyte-associated protein 4 (CTLA4), is the first drug in history to significantly prolong the survival period of patients with this highly malignant tumor." (PMID 35312867, 2022). "To further enhance the effect of combining APR-246 with ICB, we tested dual ICB using a combination of antibodies that block PD-1 and cytotoxic T lymphocyte–associated antigen 4 (CTLA-4), a strategy that has been shown to elicit a high response rate in patients with melanoma." (PMID 36106631, 2022). "In addition, the mechanism underlying the clinical benefit of HRRmut melanoma to anti-CTLA-4 needs to be further interpreted by basic research." (PMID 35990677, 2022). "Indeed, mice and melanoma patients with low frequencies of these tumor-associated myeloid subsets respond less favorably to anti-PD-1 and anti-CTLA-4 ICI and have worse overall clinical outcomes." (PMID 35444175, 2022). "Moreover, numbers of CD226+CD8+ TILs in pre-treatment tumor biopsies of melanoma patients are associated with improved progression-free survival following single anti-PD-1 therapy or anti-PD-1/anti-CTLA4 co-blockade." (PMID 34367161, 2021). "Interestingly, an increased level of circulating MDSC was observed in melanoma patients and associated with a resistance to anti-CTLA-4 therapy." (PMID 34206425, 2021).
melanoma (continued). "In addition to the experimental validation, our computational analysis with transfer learning demonstrated that the NK cell activation signature is associated with improved overall survival and anti-CTLA-4 response in melanoma patients." (PMID 34376232, 2021). "Ipilimumab is a monoclonal antibody (mAb) that enhances T cell activity by specifically targeting cytotoxic T-lymphocyte-associated protein 4 (CTLA-4) and was the first drug to be used in the clinic to significantly prolong survival in patients with advanced melanoma." (PMID 34433460, 2021). "Recent advances in immune checkpoint blockade (ICB) therapy, such as targeting programmed cell death protein 1 (PD-1)/PD-ligand 1 (PD-L1) and/or cytotoxic T-lymphocyte-associated protein 4 (CTLA-4), illustrate the power of enhancing the patient’s endogenous anti-melanoma immune responses." (PMID 34092233, 2021). "Progress in immunology has identified aberrant expression of immune check point regulators, such as programmed death-1 (PD-1) and cytotoxic T-lymphocyte associated protein 4 (CTLA-4), that can dampen host anti-tumor immune response and facilitate melanoma growth." (PMID 34769150, 2021). "According to this proposed hypothesis, further data analysis was conducted to compare the efficacy of anti-PD-1/L1 and anti-CTLA-4 therapies in patients with MAP2K1/2-mutated melanoma." (PMID 35069558, 2021). "For instance, immunotherapeutic approaches such as administration of Anti-PD1 (nivolumab, pembrolizumab) alone, or the combination of anti-PD1 with anti-cytotoxic T lymphocyte-associated protein 4 (CTLA4) ipilimumab has raised the survival of patients who suffer from advanced stages of melanoma." (PMID 33968718, 2021). "Anti-CTLA-4 treatment might be more effective than anti-PD-1 therapy for patients with MAP2K1/2-mutated melanoma." (PMID 35069558, 2021). "One retrospective study has systemically evaluated the risk of infection in 748 melanoma patients receiving ICIs (CTLA-4, PD-1, and/or PD-L1): 658 (73.2%) received ipilimumab, 52 (5.7%) received nivolumab, 83 (9.2%) received pembrolizumab, and 105 (11.7%) received a combination therapy." (PMID 34571876, 2021). "Due to the lack of available data, we could not compare the differences in the efficacy of anti-CTLA-4 monotherapy and combination therapy involving both anti-CTLA-4 anti-PD-1 in patients with MAP2K1/2-mutated melanoma in this study." (PMID 35069558, 2021). "No therapy has shown to increase overall survival (OS) of patients with advanced BRAFV600 wild-type melanoma (50% of melanoma patients) who progress beyond treatment with programmed cell death 1 (PD-1) and cytotoxic T-lymphocyte-associated antigen 4 (CTLA-4) immune checkpoint inhibitors (ICI)." (PMID 33921947, 2021). "Furthermore, mice bearing melanoma tumors deficient in IFN-γ receptor 1 (IFNGR1) had impaired tumor rejection after CTLA-4 blockade." (PMID 33777008, 2021). "Immuno-oncology (IO) agents, targeting immune checkpoint molecules such as cytotoxic T-lymphocyte associated protein-4 (CTLA-4) and programmed cell death-1 (PD-1), have revolutionized melanoma treatment and outcomes, achieving significant response rates and remarkable long-term survival." (PMID 34771465, 2021). "Another recent multicenter retrospective analysis investigated the retreatment with BRAFi and MEKi combination in 51 patients with metastatic BRAF-mutated melanoma, previously progressed after receiving kinase inhibitors (BRAFi and MEKi or BRAFi alone) and immunotherapy (anti-PD-1 or anti-CTLA-4)." (PMID 34136385, 2021). "With an innovation-based view, we suggest that for patients with MAP2K1/2-mutated melanoma, anti-CTLA-4 therapy might be more effective than anti-PD-1 monotherapy." (PMID 35069558, 2021). "Interestingly, in melanoma patients treated with cytotoxic T-lymphocyte-associated protein 4 (CTLA-4) inhibitor tremelimumab, an association was observed between immune-related toxicity and whole blood RNA expression after 30 days of treatment." (PMID 34572887, 2021).